PRMT5 (protein arginine methyltransferase 5)
Diseases named in the same sentence as PRMT5 in open-access papers (continued):
Sharing a sentence is not in itself a finding about the gene and the disease.
colorectal cancer (continued). "Collectively, our findings uncover that PRMT5 controls human colorectal cancer cell proliferation via activation of Akt, but not ERK1/2 or PTEN/mTOR signaling pathways." (PMID 33495409, 2021). "To further investigate the enzyme activity of PRMT5 was required or not for the colorectal cancer cell proliferation, we used GSK591, a PRMT5 specific inhibitor, to treat HCT116 cells, and the SDMA expression was assessed." (PMID 33495409, 2021). "It is implied that PRMT5 promotes colorectal cancer cells growth and EMT via activation of Akt, but not ERK and mTOR signaling pathway." (PMID 33495409, 2021). "Moreover, a previous study has shown that the depletion of PRMT5 significantly reduces the expression of phospho-ERK1/2 and phospho-mTOR in colorectal cancer cells." (PMID 33495409, 2021). "In addition, the overexpression of PRMT5 R368A (a methyltransferase‐inactive mutant of PRMT5) failed to increase the proliferation of colorectal cancer cells." (PMID 40279519, 2025). "Moreover, PRMT5 controls human colorectal cancer cell proliferation via the activation of Akt, but not ERK1/2 or PTEN/mTOR signaling pathways." (PMID 33495409, 2021). "To date, on the other hand, there is no clear evidence that PRMT5 and its enzyme activity regulates Akt activity to modulate colorectal cancer cell proliferation and EMT, although it has been reported that overexpression of PRMT5 promoted Akt activation (phosphorylation) in 293T cells." (PMID 33495409, 2021). "PRMT5 could be repressed by N-alpha-acetyltransferase 40 (NAA40), which results in downregulating key oncogene expressions, upregulating tumor suppressor genes levels, and finally leading to inhibiting colorectal cancer cell growth." (PMID 34124017, 2021). "Our study also proves that PRMT5 promotes cell proliferation and EMT in human colorectal cancer via activation of the EGFR/Akt/GSK3β signaling axis, but not ERK1/2 or PTEN/mTOR signaling pathways, which is strongly linked to the PRMT5 enzyme activity." (PMID 33495409, 2021). "Loss of NAT2, a non-essential enzyme involved in drug metabolism, in colorectal cancers emerged as an attractive target conceptually different from synthetic lethality (ENO2, PRMT5, ME3) or targeting genes essential for cell survival (POLR2A, RPA70, or PSMC2)." (PMID 32161261, 2020). "Furthermore, in vivo functional experiments revealed that when PRMT5 was knocked out, NEDD4L knockdown failed to promote colorectal cancer liver metastasis." (PMID 40279519, 2025). "In our study, we show that PRMT5 could activate Akt in colorectal cancer cells independent of ERK1/2, PTEN, and mTOR signaling, using PRMT5 stable knockdown cell lines and specific inhibitor GSK591, which is required for PRMT5 enzyme activity." (PMID 33495409, 2021).
prostate carcinoma (52 papers, 2012 to 2025). A carcinoma that arises from epithelial cells of the prostate gland. "Suppressed prostate cancer progression was observed in various genetic mouse models expressing the FUBP1 mutant deficient in PRMT5-mediated methylation." (PMID 39146021, 2024). "In prostate cancer cells, the androgen receptor (AR) promoter was shown to be an epigenetic target of PRMT5, and knockdown of PRMT5 caused a reduction in H4R3me2 marks at the AR promoter and a subsequent reduction in AR expression." (PMID 37795443, 2023). "Aside from phosphorylation, a study showed that the E3 ubiquitin ligase CHIP negatively regulates PRMT5 expression by promoting PRMT5 degradation through K48-linked ubiquitination in the presence of the HSP90 inhibitor 17-AAG in prostate cancer cells." (PMID 37173967, 2023). "Although less characterized, the ubiquitination of PRMT5 by carboxyl terminus of heat shock cognate 70-interacting protein (CHIP) at multiple lysine residues has been reported to cause PRMT5 proteasomal degradation in prostate cancer cells." (PMID 34685445, 2021). "Multiple transcription factors have been implicated in PRMT5 overexpression in different cancer subtypes, including nuclear transcription factor Y (NF-Y) in prostate cancer, nuclear factor kappa B (NF-κB) in diffuse large B-cell lymphoma, and the fused MLL-1 protein in acute myeloid leukemia (AML)." (PMID 38666828, 2024). "Translocation of PRMT5 and p44 from the nucleus to the cytoplasm is associated with prostate tumorigenesis demonstrating that cytoplasmtic PRMT5 and p44 are required for growth of prostate cancer." (PMID 27480244, 2016). "Similar ceRNA-driven mechanisms involving miR-376a-3p/YAP1 in glioma, miR-590-5p/METTL3 in lung adenocarcinoma, and miR-376a-3p/PRMT5 in prostate cancer further underscore its oncogenic potential." (PMID 40903777, 2025). "The ceRNA mechanism is also evident in lung adenocarcinoma through the miR-590-5p/METTL3 axis and in prostate cancer via modulation of PRMT5 through miR-376a-3p." (PMID 40903777, 2025). "In prostate cancer, PRMT5 also epigenetically activates the expression of CSF2, promoting the infiltration of immunosuppressive neutrophils and monocytes." (PMID 41204384, 2025). "In prostate cancer, PRMT5 catalyzes H4R3 methylation at the AR promoter to activate AR transcription." (PMID 40919714, 2025). "While nuclear PRMT5 inhibits cell growth in the benign prostate epithelium, cytoplasmic PRMT5 is essential for cancer cell growth in premalignant and prostate cancer tissues." (PMID 38791992, 2024). "Considering the importance of FUBP1 methylation in prostate cancer, upstream signaling regulating PRMT5-mediated FUBP1 methylation was assessed." (PMID 39146021, 2024). "We also determined that nanocomplex (NC) delivery of a competitive peptide to block interaction of FUBP1 with PRMT5 is a potential therapeutic strategy to treat prostate cancer by preventing PRMT5-mediated FUBP1 methylation." (PMID 39146021, 2024). "The expression of PRMT5, FUBP1, and meFUBP1 seems to be correlated in prostate cancer cell lines, supporting a potential biomarker role of meFUBP1 for PRMT5 activity." (PMID 39146021, 2024). "Endogenous PRMT5, FUBP1, and meFUBP1 were detected in all prostate cancer–related cell lines, highlighting that the PRMT5-mediated FUBP1 methylation is a universal event in prostate cancer." (PMID 39146021, 2024). "We have also explored the ability of JNJ-64619178 in targeting FIR-induced NED and NE-like cells in prostate cancer since PRMT5 is required for NE-like cell survival." (PMID 36959798, 2023). "In this study, we demonstrated that therapeutic targeting of PRMT5 with JNJ-64619178 downregulates the expression of DSB repair proteins in prostate cancer cells." (PMID 36959798, 2023).
prostate carcinoma (continued). "Clinically actionable opportunities associated with PRMT5 regulation of DDR genes have been largely unexplored, although several studies have indicated susceptibility of blood and prostate cancers to ATM inhibitors or irradiation." (PMID 37861290, 2023). "Consistent with its epigenetic function, PRMT5 induces symmetric dimethylation of H4R3 (H4R3me2s) to activate DDR gene expression in irradiated prostate cancer cells." (PMID 37861290, 2023). "Among the four types of cancers analyzed, breast and prostate cancer cell lines show a stronger correlation between PRMT5 and DDR gene expression." (PMID 37861290, 2023). "In prostate cancer, Owens and colleagues demonstrated a unique mechanism by which PRMT5 and cofactor pICln coordinate H4R3me2s-mediated transcriptional activation at DDR promoters in response to irradiation." (PMID 37861290, 2023). "Protein arginine methyltransferase 5 (PRMT5) gets upregulated upon ionizing radiation treatment and epigenetically activates DNA damage repair genes in prostate cancer cells." (PMID 36959798, 2023). "For instance, PRMT5 epigenetically activates the transcription of the androgen receptor and facilitates prostate cancer cell growth." (PMID 33495409, 2021). "In prostate cancer, the nuclear PRMT5 is responsible for proliferation inhibition and is related to the prolongation of survival rate while the cytoplasmic PRMT5 promotes cell proliferation." (PMID 34513846, 2021). "A similar prognostic potential of high PRMT5 expression in the nucleus and/or the cytoplasm has been reported in brain, lung, ovarian, skin, and prostate cancers." (PMID 34685445, 2021). "CLNS1A cooperates with the protein PRMT5 and functions as an epigenetic activator of AR transcription in castration resistance prostate cancer." (PMID 34439272, 2021). "For example, protein arginine methyltransferase 5 (PRMT5) methylates H2A at residue arginine 3 (H2AR3) which serves as an epigenetic activator to promote prostate cancer growth." (PMID 34140951, 2021). "For example, PRMT5 is a potential target for the inhibition of prostate cancer growth as it potentiates prostate cancer tumorigenesis by methylating AR genes important for tumor progression." (PMID 33440687, 2021). "We have previously identified TRIM21 as a potential interacting partner of PRMT5 by mass spectrometry in prostate cancer cells." (PMID 32023548, 2020). "Deng X et al11 found that PRMT5 promotes prostate cancer cell growth by epigenetically activating transcription of the androgen receptor (AR) in prostate cancer cells." (PMID 31851779, 2020). "Our previous mass spectrometry identified several E3 ligases include CHIP and TRIM21 as interacting proteins of PRMT5 in prostate cancer cells." (PMID 32023548, 2020). "Alternatively, protein arginine methyltransferase 5 (PRMT5) was described as a prostate cancer oncogene driving cancer cell growth through epigenetic inactivation of several tumor suppressors through histone arginine methylation at H4R3." (PMID 29888169, 2018). "In the case of prostate cancer cells, PRMT5 inappropriately modifies the androgen receptor, a protein that regulates the growth of normal prostate cells." (PMID 27183006, 2016). "Expression of PRMT5 and p44 in lung and prostate cancer cells was silenced and their target genes were identified." (PMID 27480244, 2016). "Regulation of identified genes by PRMT5 and p44 was further demonstrated in multiple lung and prostate cancer cell lines and in mouse lungs as well as during lung tumorigenesis." (PMID 27480244, 2016). "In agreement with this conclusion, PRMT5 has been found over-expressed in leukemia, lymphoma, colorectal, lung, ovarian, and prostate cancer." (PMID 27480244, 2016). "In the cytoplasm, PRMT5 was essential for prostate cancer cell growth; in contrast, in the nucleus it inhibited cell growth." (PMID 24326178, 2013).
prostate carcinoma (continued). "In the human prostate, PRMT5 and p44 are resident in the nucleus of benign epithelial cells, whereas in prostate cancer cells, PRMT5 and p44 localize in the cytoplasm." (PMID 22952863, 2012). "In our current study, immunostaining with the anti-PRMT5 antibody indicated that PRMT5 is predominantly cytoplasmic in prostate cancer PC3 and LNCaP cells." (PMID 22952863, 2012). "On the other hand, the forced nuclear localization of p44 or PRMT5 inhibited the growth of prostate cancer cells." (PMID 22952863, 2012). "In the current study, we found that cytoplasmic PRMT5 is essential for the growth of prostate cancer cells, whereas nuclear PRMT5 inhibits prostate cancer cell growth." (PMID 22952863, 2012). "PRMT5 and p44 are co-expressed in the cytoplasm, and both are required for the growth of prostate cancer cells." (PMID 22952863, 2012). "By using a subcellular localization assay, we found that PRMT5 contains three strong NES sequences that determine its predominant cytoplasmic localization in prostate cancer cells." (PMID 22952863, 2012). "AS1411 reduced the nuclear/cytoplasmic ratio of the nucleolin-interacting protein PRMT5 (Protein Arginine Methyltransferase 5) in DU145 prostate cancer cells." (PMID 22693611, 2012). "When localized in the cytoplasm of prostate cancer cells, PRMT5 is essential for cell growth; in contrast, the nuclear PRMT5 suppresses cell growth." (PMID 22952863, 2012). "Furthermore, in castration-resistant prostate cancer, PRMT5 inhibition synergizes with anti-PD-1 therapy to enhance anti-tumor activity." (PMID 41204384, 2025). "PRMT5 has been reported to promote prostate cancer development via multiple mechanisms." (PMID 39146021, 2024). "Notably, CLNS1A cooperates with the protein arginine methyltransferase 5, which functions as an epigenetic activator of androgen receptor transcription in castration-resistant prostate cancer." (PMID 39857609, 2024). "Additionally, PRMT5 promotes the growth of prostate cancer cells by epigenetically binding to the promoter region of the androgen receptor gene." (PMID 39678513, 2024). "This supports the concept that precision intervention on PRMT5 function may be used to treat prostate cancer." (PMID 39146021, 2024). "Considering the pivotal role and clinical relevance of PRMT5 inhibitors in cancer progression, we explored whether PRMT5 inhibitors could serve as an effective therapeutic strategy for prostate cancer characterized by low ZMYND11 expression." (PMID 39341825, 2024). "For instance, PRMT5 exhibits divergent roles in the cytoplasm and nucleus of prostate cancer cells." (PMID 38791992, 2024). "Interestingly, the PRMT5 cofactor chloride nucleotide-sensitive channel 1A (pICLn) is reported to play a role in PRMT5-H4R3me2–mediated gene regulation in prostate cancer." (PMID 37861290, 2023). "Previous works by our and other groups have associated PRMT5 with the regulation of DDR genes in blood and prostate cancers, although the precise mechanisms remain unclear and therapeutic opportunities continue to be explored." (PMID 37861290, 2023). "Interestingly, C220 partially reduced the expression of global H4R3me2s, which has been reported as one mechanism of a PRMT5-mediated DNA damage response in prostate cancer." (PMID 37861290, 2023). "Members of the protein arginine methyltransferase family are also aberrantly expressed in prostate cancer cells, e.g., PRMT5, which catalyses histone arginine methylation at histone H4R3, causing epigenetic inactivation of several tumour suppressors and thus promoting prostate cancer cell growth." (PMID 35205419, 2022). "PRMT5 mediates radiotherapy resistance in prostate cancer, implying that targeting PRMT5 splicing may be an effective radiosensitization strategy for cancer radiotherapy." (PMID 36499164, 2022). "We previous showed an essential role of PRMT5 and p44 in growth of lung and prostate cancer cells." (PMID 27480244, 2016).
prostate carcinoma (continued). "This provides a rationale for targeting PRMT5 in TMPRSS2:ERG positive prostate cancers." (PMID 27183006, 2016). "The AR-inhibitory function of PRMT5 is restricted to TMPRSS2:ERG-positive prostate cancer cells." (PMID 27183006, 2016). "In prostate cancer cells PRMT5 expression is primarily cytoplasmic and promotes growth." (PMID 25115397, 2014). "Here, we demonstrated that PRMT5 predominantly localized in the cytoplasm of prostate cancer cells." (PMID 22952863, 2012). "To evaluate p44 and PRMT5 nuclear and cytoplasmic subcellular localization in areas of benign, premalignant (prostatic intraepithelial neoplasia [PIN]), and cancer tissues, we performed immunohistochemical staining for p44 and PRMT5 in 19 samples derived from patients with prostate cancer." (PMID 22952863, 2012). "Because cytoplasmic PRMT5 and p44 are required for the growth of prostate cancer cells, and nuclear PRMT5 and p44 inhibit cancer cell growth, nucleocytoplasmic transport of PRMT5 and p44 might be essential event during prostate tumorigenesis." (PMID 22952863, 2012). "To determine whether PRMT5 plays a role in prostate cancer, we tested whether silencing PRMT5 expression in LNCaP cells would affect their growth." (PMID 22952863, 2012). "However, it is tempting to speculate that this effect could result from the known interaction between ERG and PRMT5 that can only occur in TMPRSS2:ERG fusion positive prostate cancers." (PMID 40554389, 2025). "As PRMT5-mediated FUBP1 methylation is not limited to prostate cancer, the clinical application of this competitive peptide may extend to other cancers, and HA/BPAE/peptide NCs could be used to treat various cancers with reduced systemic side effects and improved therapeutic efficacy." (PMID 39146021, 2024). "Hence, targeting PRMT5 can be a therapeutic strategy for the radiosensitization of prostate cancer." (PMID 36959798, 2023). "Thus, both PRMT5 and p44 are required for the growth of prostate cancer cells." (PMID 22952863, 2012). "In the context of prostate cancer, BHLHE22 and PRMT5 assemble a transcriptional complex that initiates CSF2 transcription, which then attracts many immunosuppressive neutrophils and monocytes, promoting the tumor’s metastasis to the bones." (PMID 40242775, 2025). "The PRMT5/MEP50 complex is well recognized for its arginine methylase activity and promotes the progression of multiple cancers, including prostate cancer." (PMID 39146021, 2024). "A competitive peptide, which was delivered through nanocomplexes, disrupted the interaction of FUBP1 with PRMT5, blocked FUBP1 methylation, and inhibited prostate cancer development in various preclinical models." (PMID 39146021, 2024). "Here we found that PRMT5 methylates FUBP1 at R359/R361/R363, which was important for the oncogenic effect of FUBP1 in prostate cancer." (PMID 39146021, 2024). "We reported earlier that prostate cancer cells undergo NED and transdifferentiate into NE-like cells post FIR treatment with the cumulative treatment of 40 Gy (2 Gy/day, 5 days/week) and PRMT5 protein gets upregulated in response to FIR." (PMID 36959798, 2023). "In this study, we targeted PRMT5 with JNJ-64619178 and assessed its effect on DNA damage repair gene activation, radiosensitization, and FIR-induced NED in prostate cancer." (PMID 36959798, 2023). "PRMT5 and p44/MED50/WD45/WDR77 co-localize in the cytoplasm, and both are required for the growth of prostate cancer cells in an PRMT5 methyltransferase activity-dependent manner." (PMID 22952863, 2012). "The patterns of p44 and PRMT5 expression in benign prostate epithelial cells and in PIN and prostate cancer cells were almost identical in terms of subcellular localization, consistent with our previous report of p44 and PRMT5 co-localization in the testis." (PMID 22952863, 2012). "In CRC, prostate cancer, and HCC, PRMT4, PRMT5, and PRMT9 drive EMT via PI3K/AKT signaling." (PMID 41204384, 2025).